ROR1 (ROR family WNT receptor 1)
Diseases named in the same sentence as ROR1 in open-access papers (continued):
Sharing a sentence is not in itself a finding about the gene and the disease.
endometrial cancer (10 papers, 2020 to 2025). Primary or metastatic malignant neoplasm involving the endometrium (mucous membrane that lines the endometrial cavity). "The aim of this study was to investigate the role of ROR1 through in vitro experiments in endometrial cancer cell lines." (PMID 37241228, 2023). "Materials and Methods: ROR1 expression was identified in endometrial cancer cell lines using Western blot and RT-qPCR." (PMID 37241228, 2023). "Many malignancies, including ovarian and endometrial cancer, show an abnormal expression of the Wnt signalling receptor ROR1." (PMID 36046368, 2022). "We previously reported that a high ROR1 level was associated with shorter survival in high-grade serous ovarian cancer (HGSOC) and endometrial cancer (EC) patients." (PMID 35456672, 2022). "Our previous in vitro study in EC showed ROR2 overexpression in combination with silencing its sister receptor ROR1 inhibited the metastatic potential of KLE endometrial cancer cells more than either of the modifications alone." (PMID 33494187, 2021). "This study confirms the role of ROR1 plays in endometrial cancer and warrants the future application of ROR1-targeting therapies in endometrial cancer patients." (PMID 32807831, 2020). "This study supports the oncogenic role of ROR1 in endometrial cancer, and warrants investigation of future application of ROR1-targeting therapies in endometrial cancer patients." (PMID 32807831, 2020). "We examined the protein expression of key components in PI3K/AKT, GCN2/ATF4, epithelial–mesenchymal transition and apoptosis pathways in ROR1‐positive endometrial cancer cell lines HEC‐1‐B, KLE, ARK1, RL95‐2 and Ishikawa, following treatment with GZD824 for 48 h." (PMID 39739675, 2025). "Targeting ROR1 can inhibit cancer metastasis and may be a potential treatment method for patients with endometrial cancer who exhibit chemoresistance." (PMID 37241228, 2023). "We previously reported that silencing ROR1 could inhibit the proliferation and metastatic potential of ovarian and endometrial cancer cells in vitro." (PMID 35456672, 2022). "Thus, it could be hypothesised that ROR1 also regulated the EMT in endometrial cancer and modulation in ROR1 could alter cell migration and invasion ability." (PMID 32807831, 2020). "The effects of ROR1 on cell proliferation, invasion, migration, and epithelial-mesenchymal transition (EMT) markers were analyzed in two endometrial cancer cell lines (HEC-1 and SNU-539) using either ROR1 silencing or overexpression." (PMID 37241228, 2023). "Alternately, miR-379-5p inhibits endometrial cancer cell proliferation and invasion via downregulation of RTK-like orphan receptor 1 (ROR1) levels." (PMID 34592879, 2021). "The aim of this study was to investigate the role of ROR1 and ROR2 in endometrial cancer via immunohistochemistry (IHC) in a large endometrial cancer patient cohort (n = 499) and through in vitro analysis in endometrial cancer cell lines." (PMID 32807831, 2020). "The effect of ROR1 and/or ROR2 modulation on cell proliferation, adhesion, migration and invasion was analysed in two endometrial cancer cell lines (KLE and MFE-296)." (PMID 32807831, 2020). "ROR1 silencing and ROR2 overexpression significantly inhibited proliferation of KLE endometrial cancer cells and decreased migration." (PMID 32807831, 2020). "A significant decrease in endometrial cancer specific OS and PFS was observed in patients with high ROR1 expression (p = 0.049 and p = 0.021, respectively) in the clinical cohort." (PMID 32807831, 2020). "The non-canonical Wnt signalling receptor ROR1 is aberrantly expressed in numerous cancers, including ovarian and endometrial cancer." (PMID 35456672, 2022).
neuroblastoma (10 papers, 2014 to 2025). Neuroblastoma (NB) is the most common solid, extracranial childhood tumor. "In cytotoxicity experiments, the authors demonstrated that the combination of an oncolytic virus and anti-ROR1-CAR-NK cells significantly enhanced the cytotoxic effect of the latter on SKNFI neuroblastoma cells." (PMID 41369346, 2025). "ROR1/2 were initially discovered in a neuroblastoma cell line in a PCR screen for receptor tyrosine kinases and were formerly named as neurotrophic tyrosine kinase receptor-related (NTRKR1/2)." (PMID 24752542, 2014). "Moreover, the combination of oncolytic virus and anti-ROR1-CAR-NK cells significantly increased the survival of NSG mice bearing human neuroblastoma xenografts, demonstrating the effectiveness of this combination in vivo." (PMID 41369346, 2025). "This group showed that anti-ROR1 antibodies could target neuroblastoma cells for natural killer (NK)-mediated cell killing, while CAR T cells targeting ROR1+ neuroblastoma cells are currently under development." (PMID 34716856, 2022). "Altogether, we found that RYK and ROR2, but not ROR1, are robustly associated with worse outcome in neuroblastoma." (PMID 34716856, 2022). "Interestingly, KIT clustered with ROR1, which is also expressed early in development and is a marker for cell migration and invasiveness in neuroblastoma and other cancers." (PMID 25884760, 2015). "Furthermore, ROR2 expression analysis in cancer cell lines (CCLE, Broad Institute) suggests a relatively high mRNA level in neuroblastoma cells, showing the highest average expression among all cancer cell lines, while ROR1 showing low specificity for neuroblastoma cell lines." (PMID 34716856, 2022). "Together, these data suggest that the WNT modifying pseudokinases ROR2 and RYK represent potential novel therapeutic targets for neuroblastoma treatment and that current research on immuno-therapeutic strategies against ROR1 might need to be re-evaluated in favor of ROR2 and RYK." (PMID 34716856, 2022). "The RTK genes ROR1 and ROR2 were originally cloned form the neuroblastoma cell line SH-SY5Y." (PMID 34716856, 2022). "This is further supported by a recent study describing a role for ROR1, but not ROR2, in retinoic acid-induced neuroblastoma differentiation." (PMID 34716856, 2022).
prostate carcinoma (8 papers, 2018 to 2025). A carcinoma that arises from epithelial cells of the prostate gland. "ROR1 has great potential as an emerging cancer-associated molecular target that can be used to subtype and treat prostate cancer." (PMID 39000112, 2024). "Since ARneg-AI prostate cancers lack cancer-associated markers, ROR1 inhibition by strictinin may still be a suitable option for DU145-like clinical prostate cancer." (PMID 38213538, 2023). "The results from our experiments provide evidence for PGG to be an ROR1 inhibitor in prostate cancer cells and shows potential for the clinical treatment of ARneg-AI CRPC." (PMID 39000112, 2024). "We previously identified that DU145 cells, another ARneg-AI prostate cancer, have a moderate expression of ROR1 compared to PC3 cells." (PMID 39000112, 2024). "Through our experiments, we have established PGG as an ROR1 inhibitor that exerts significant anti-cancer effects against ARneg-AI prostate cancer cells." (PMID 39000112, 2024). "In this study, we identify that Penta-O-galloyl-β-D-glucose (PGG), a plant-derived gallotannin small molecule inhibitor, modulates ROR1-mediated oncogenic signaling and mitigates prostate cancer phenotypes." (PMID 39000112, 2024). "In this study, we have identified the importance of ROR1 as a driver of cancer aggression in ARneg-AI prostate cancer, which is a form of prostate cancer that exhibits castration resistance and lacks a targetable AR." (PMID 39000112, 2024). "Our results suggest that ROR1 is an important driver of cancer aggression in ARneg-AI prostate cancer that exhibits castration resistance and lacks a targetable AR." (PMID 39000112, 2024). "By identifying the molecular mechanism by which strictinin negatively impacts prostate cancer, we highlight the importance of ROR1 as a driver of aggressive prostate cancer." (PMID 38213538, 2023). "Our findings suggest that strictinin can selectively target prostate cancers that express ROR1 to hinder anti-apoptosis, migration, invasion, EMT, and cell cycle progression." (PMID 38213538, 2023). "The goal of this study was to selectively target prostate cancer cells that have high levels of oncogenic protein Receptor tyrosine kinase-like orphan receptor 1 (ROR1) by using strictinin, a small molecule ROR1 inhibitor." (PMID 38213538, 2023). "In this study, we identify that strictinin inhibits ROR1 and modulates the subsequent downstream oncogenic signaling cascade in ARneg-AI prostate cancer cells." (PMID 38213538, 2023). "The natural compound strictinin, as well as the emerging molecular target ROR1, have marked potential for the clinical treatment of aggressive ARneg-AI prostate cancers." (PMID 38213538, 2023). "The data from this study establishes strictinin as a potential therapeutic agent that targets ARneg-AI prostate cancer with elevated ROR1 expression to reduce the migration, invasion, cell cycle progression, and survival of prostate cancer." (PMID 38213538, 2023). "Our results indicate that strictinin can be selectively lethal, anti-migratory, and anti-invasive to ARneg-AI prostate cancer cells by modulating ROR1-mediated AKT-GSK3β signaling." (PMID 38213538, 2023). "It is worth investigating strictinin as a ROR1 inhibitor in other cancers that display elevated levels of ROR1 expression to further expand on the findings in this study that identify the anti-cancerous effects of strictinin in ARneg-AI prostate cancer." (PMID 38213538, 2023). "Genes encoding FZD2-5, FZD8, VANGL1, ROR1, RYK, LGR4, LRP5 and 6, and GPC4 were highly expressed in at least three prostate cancer cell lines." (PMID 29717114, 2018). "We opted to treat PC3 since these cells represent an aggressive and clinically difficult to treat ARneg-AI cancer that demonstrated the highest levels of ROR1 expression in comparison to normal prostatic epithelial cells and other prostate cancer cell lines such as DU145." (PMID 39000112, 2024).
prostate carcinoma (continued). "DU145, an ARneg-AI prostate cancer cell line, exhibited moderate levels of ROR1 expression." (PMID 39000112, 2024). "Our study reveals that strictinin may have marked utility for the treatment of ARneg-AI prostate cancer and that ROR1 is an effective marker for targeted prostate cancer treatment." (PMID 38213538, 2023). "ROR1 is also uniquely overexpressed in a wide variety of cancers, including prostate cancer." (PMID 38213538, 2023). "Since ROR1 expression is upregulated in prostate cancer, we hypothesized that strictinin could target aggressive prostate cancer." (PMID 38213538, 2023). "Furthermore, our previous research identified that ROR1 was an important molecular marker for ARneg-AI prostate cancer cell lines (PC3 and DU145)." (PMID 38213538, 2023). "Utilizing less docetaxel in combination with strictinin may help alleviate harsh chemotherapy side effects in prostate cancer patients while enabling more specificity of therapy by strictinin-induced targeting of ROR1." (PMID 38213538, 2023). "ROR1 is an emerging molecular target that can be utilized for treating prostate cancer." (PMID 38213538, 2023). "However, for reasons currently unknown, ROR1 is uniquely upregulated in many cancers, including prostate cancer." (PMID 39000112, 2024). "Furthermore, PGG may be a selective and potent anti-cancer agent capable of treating ROR1-expressing prostate cancers." (PMID 39000112, 2024). "Hence, it is necessary to continue exploring cancer-associated markers, such as oncofetal Receptor Tyrosine Kinase like Orphan Receptor 1 (ROR1), which may serve as a form of targeted prostate cancer therapy." (PMID 39000112, 2024). "Hence, we wanted to explore whether ROR1 inhibitor strictinin can selectively target aggressive ARneg-AI prostate cancer." (PMID 38213538, 2023). "Hence, prostate cancers that exhibit elevated levels of ROR1 may be specifically targeted by established forms of therapy such as immunotherapy or small molecule inhibitors." (PMID 38213538, 2023). "Strictinin suppresses ROR1 expression and modulates downstream signaling cascades that play a role in anti-apoptosis, migration, invasion, and EMT, which mitigates prostate cancer cell aggressiveness." (PMID 38213538, 2023). "Since we evaluated how strictinin affected ROR1-mediated AKT-GSK3β signaling in PC3 cells, we also wanted to determine the impact of strictinin on ROR1 and AKT-GSK3β signaling in DU145, which is another ARneg-AI, ROR1 expressing prostate cancer cell line." (PMID 38213538, 2023). "Given the lack of targeted markers for ARneg-AI prostate cancer, ROR1 inhibition may still be a viable option for clinical prostate cancers that exhibit the characteristics of DU145 cells." (PMID 39000112, 2024). "Prostate cancer cells (PC-3) stimulated by Wnt ligands (Wnt5A, Wnt10B) were analyzed by Cy3-PLA for the co-localization of FZD6 and co-receptors (canonical: LRP6, non-canonical: ROR1) at the single-cell level." (PMID 34769487, 2021).
B-cell lymphoma (7 papers, 2017 to 2024). "Another anti-ROR1 antibody drug conjugate, consisting of the huXBR1-402 antibody conjugated with anthracycline derivative (PNU) showed inhibitory effect on ROR1 positive B-cell lymphoma in vivo and MCL in vitro." (PMID 39551787, 2024). "Some other targets are currently being evaluated for B cell lymphoma, such as CD20 (NCT03576807, NCT03664635), CD22, receptor tyrosine kinase-like orphan receptor 1 (ROR1) (NCT02706392), and Ig kappa chain, to address these challenges." (PMID 33167514, 2020).
colorectal cancer (7 papers, 2010 to 2023). A primary or metastatic malignant neoplasm that affects the colon or rectum. "In conclusion, the XIST/miR‐30a‐5p/ROR1 axis could be deemed as pivotal markers underlying colorectal cancer, and administration of atractylenolide II might improve the chemotherapeutic efficacy for colorectal cancer." (PMID 30907503, 2019). "Our results demonstrated that XIST and ROR1 expressions were dramatically up‐regulated, yet miR‐30a‐5p expression was down‐regulated within colorectal cancer tissues (P < 0.05)." (PMID 30907503, 2019). "Multivariate Cox regression analysis confirmed that ROR1 is an independent prognostic marker in colorectal cancer (p = 0.002, HR = 2.08, 95% CI: 1.314–3.292)." (PMID 28427197, 2017). "Western blot analysis and immunohistochemistry showed that the expression of ROR1 in colorectal cancer was significantly higher than that in the adjacent normal tissues." (PMID 28427197, 2017). "Further examination of human colorectal cancer samples revealed higher expression of Ror1 in colorectal cancer tissues than in adjacent normal colon tissues (data not shown)." (PMID 20587074, 2010). "Interestingly, atractylenolides not only switched the expressions of XIST, miR‐30a‐5p and ROR1 within colorectal cancer cells but also significantly intensified the chemosensitivity of colorectal cancer cells (P < 0.05)." (PMID 30907503, 2019). "This investigation was conducted to elucidate whether atractylenolide II could reverse the role of lncRNA XIST/miR‐30a‐5p/ROR1 axis in modulating chemosensitivity of colorectal cancer cells." (PMID 30907503, 2019). "This study aimed to explore the prognostic significance of ROR1 in colorectal cancer." (PMID 28427197, 2017). "We also examined ROR1 expression in colorectal cancer cells by flow cytometry." (PMID 28427197, 2017). "Thus, our study demonstrated that ROR1 expression is correlated with malignant attributes and may serve as a novel prognostic marker and therapeutic target for colorectal cancer." (PMID 28427197, 2017).
lymph node metastasis (7 papers, 2015 to 2025). "Another study of oral cancer demonstrated that high ROR1 expression was associated with lymph node metastasis." (PMID 40723210, 2025). "ROR1 expression was positively associated with clinical stage and lymph node metastasis in colorectal cancer, for which it served as an independent prognostic marker." (PMID 33445713, 2021). "ROR1 expression was positively associated with the clinical stage and lymph-node metastasis (p < 0.01)." (PMID 28427197, 2017). "We also found a significant association between ROR1 expression and lymph node metastasis status in lung ADC patients." (PMID 27830754, 2016). "In patients with positive lymph node metastasis, higher ROR1 expression was also significantly associated with poorer survival (P < 0.001)." (PMID 27830754, 2016). "When comparing patients with skin metastases to those with lymph node metastases, we observed a significantly higher frequency of tumours with high ROR1 expression among patients with lymph node involvement (p = 0.007)." (PMID 41355329, 2025). "In subgroup analysis, high ROR1 expression showed a significantly higher rate of advanced stage or lymph node metastasis." (PMID 36557069, 2022). "Patients at advanced stages or with positive lymph node metastasis had significant higher level of ROR1 expression." (PMID 27830754, 2016). "Patients at advanced stages and those with positive lymph node metastasis expressed higher level of ROR1 (P < 0.001)." (PMID 27830754, 2016). "The log-rank test showed that in patients with different ROR1 expression levels, at different clinical stages and with different lymph node metastasis status, the median OS time were significant different (all P < 0.001)." (PMID 27830754, 2016). "Higher expression of ROR1 was observed in patients with positive lymph node metastasis in our study (P < 0.001)." (PMID 27830754, 2016). "Moreover, we also stratified the lung ADC patients with positive lymph node metastasis status by ROR1 expression level, and revealed that higher ROR1 expression was also correlated with shorter OS (both P < 0.001) by both univariate and multivariate analysis." (PMID 27830754, 2016). "The results indicate that ROR1 might serve as an independent prognostic factor for lung ADC patients with positive lymph node metastasis." (PMID 27830754, 2016). "Moreover, Chi-square test showed that ROR1 expression was correlated to gender (P = 0.028), the 7th edition of the American Joint Committee on Cancer tumor-node-metastasis (AJCC TNM) staging system and lymph node metastasis (P < 0.001)." (PMID 27830754, 2016).
acute myeloid leukemia (6 papers, 2017 to 2024). Acute myeloid leukemia (AML) is a group of neoplasms arising from precursor cells committed to the myeloid cell-line differentiation. "In mice, the knockout of miRNA miR-15/16, leading to the overexpression of the pro-survival factor BCL2 as well as ROR1, induced the development of B cell lymphoma in 23% of the animals, while 77% developed an aggressive acute myeloid leukemia (AML)." (PMID 33445713, 2021). "In addition, ROR1 was found in CD34+ acute myeloid leukemia (AML) cells and can be targeted by mAbs.In addition to hematological malignancies, aberrant expression of ROR1 was also found in a wide range of solid tumors as a biomarker and therapeutic target." (PMID 34123850, 2021). "Finally, all acute myeloid leukaemia (n = 52) and most T-cell non-Hodgkin lymphoma (n = 31/32) tested samples were negative for ROR1 via IHC." (PMID 39495778, 2024).
Ewing sarcoma (6 papers, 2015 to 2025). A small round cell tumor that lacks morphologic, immunohistochemical, and electron microscopic evidence of neuroectodermal differentiation. "Insulin-like growth factor 1 receptor (IGF-1R) and tyrosine kinase orphan-like receptor 1 (ROR1) are highly expressed in various sarcoma cell lines such as alveolar or embryonal rhabdomyosarcoma, Ewing sarcoma, fibrosarcoma and osteosarcoma." (PMID 33207697, 2020). "A recent study has reported chemotactic migration of Ewing sarcoma cells towards WNT5A, which was impaired by ROR1 silencing." (PMID 33445713, 2021).